CHUK (component of inhibitor of nuclear factor kappa B kinase complex)
Description:
Serine kinase that plays an essential role in the NF-kappa-B signaling pathway which is activated by multiple stimuli such as inflammatory cytokines, bacterial or viral products, DNA damages or other cellular stresses. Acts as a part of the canonical IKK complex in the conventional pathway of NF-kappa-B activation and phosphorylates inhibitors of NF-kappa-B on serine residues. These modifications allow polyubiquitination of the inhibitors and subsequent degradation by the proteasome. In turn, free NF-kappa-B is translocated into the nucleus and activates the transcription of hundreds of genes involved in immune response, growth control, or protection against apoptosis. Negatively regulates the pathway by phosphorylating the scaffold protein TAXBP1 and thus promoting the assembly of the A20/TNFAIP3 ubiquitin-editing complex (composed of A20/TNFAIP3, TAX1BP1, and the E3 ligases ITCH and RNF11). Therefore, CHUK plays a key role in the negative feedback of NF-kappa-B canonical signaling to limit inflammatory gene activation. As part of the non-canonical pathway of NF-kappa-B activation, the MAP3K14-activated CHUK/IKKA homodimer phosphorylates NFKB2/p100 associated with RelB, inducing its proteolytic processing to NFKB2/p52 and the formation of NF-kappa-B RelB-p52 complexes. In turn, these complexes regulate genes encoding molecules involved in B-cell survival and lymphoid organogenesis. Also participates in the negative feedback of the non-canonical NF-kappa-B signaling pathway by phosphorylating and destabilizing MAP3K14/NIK. Within the nucleus, phosphorylates CREBBP and consequently increases both its transcriptional and histone acetyltransferase activities. Modulates chromatin accessibility at NF-kappa-B-responsive promoters by phosphorylating histones H3 at 'Ser-10' that are subsequently acetylated at 'Lys-14' by CREBBP. Additionally, phosphorylates the CREBBP-interacting protein NCOA3. Also phosphorylates FOXO3 and may regulate this pro-apoptotic transcription factor. Phosphorylates RIPK1 at 'Ser-25' which represses its kinase activity and consequently prevents TNF-mediated RIPK1-dependent cell death (By similarity). Phosphorylates AMBRA1 following mitophagy induction, promoting AMBRA1 interaction with ATG8 family proteins and its mitophagic activity.
Synonyms: IKK-alpha; IkBKA; IKK-1; IKK1; NFKBIKA; IKKA; TCF16; BPS2
Tractability: Small molecule: a structure with a bound ligand is known; a high-quality ligand is known; it belongs to a druggable protein family. PROTAC: UniProt records ubiquitination sites on it; ubiquitination databases record sites on it; its protein half-life has been measured; a small molecule that binds it is known.
Target class: Enzyme; Kinase; Protein Kinase; Other protein kinase group
Chemical probes: PD082321, PD084348
Gene: Protein-coding gene on chromosome 10 (100,188,300 to 100,229,596, reverse strand). Ensembl gene ENSG00000213341.
Subcellular location: Cytoplasm; Nucleus
Subcellular location (Human Protein Atlas): Nucleoplasm; Cytosol
Pathways (Reactome):
Immune System: Activation of NF-kappaB in B cells; CLEC7A (Dectin-1) signaling; Dectin-1 mediated noncanonical NF-kB signaling; Downstream TCR signaling; ER-Phagosome pathway; FCERI mediated NF-kB activation; IKK complex recruitment mediated by RIP1; IRAK1 recruits IKK complex; IRAK1 recruits IKK complex upon TLR7/8 or 9 stimulation; Interleukin-1 signaling; MAP3K8 (TPL2)-dependent MAPK1/3 activation; Modulation of host responses by IFN-stimulated genes; NF-kB activation through FADD/RIP-1 pathway mediated by caspase-8 and -10; NIK-->noncanonical NF-kB signaling; NOD1/2 Signaling Pathway; PKR-mediated signaling; RIP-mediated NFkB activation via ZBP1; Regulation of NF-kappa B signaling; SLC15A4:TASL-dependent IRF5 activation; TAK1-dependent IKK and NF-kappa-B activation; TICAM1, RIP1-mediated IKK complex recruitment; TRAF6 mediated NF-kB activation
Disease: Constitutive Signaling by AKT1 E17K in Cancer; IKBKB deficiency causes SCID; IKBKG deficiency causes anhidrotic ectodermal dysplasia with immunodeficiency (EDA-ID) (via TLR); IkBA variant leads to EDA-ID; SARS-CoV-2 activates/modulates innate and adaptive immune responses
Signal Transduction: AKT phosphorylates targets in the cytosol; Regulation of TNFR1 signaling; TNFR1-induced NF-kappa-B signaling pathway
Cellular responses to stimuli: Turbulent (oscillatory, disturbed) flow shear stress activates signaling by PIEZO1 and integrins in endothelial cells
Gene Ontology:
Molecular function: IkappaB kinase activity; protein binding; protein heterodimerization activity; protein homodimerization activity; protein kinase activity; protein serine/threonine kinase activity; scaffold protein binding; transferrin receptor binding; ATP binding; protein-containing complex binding
Biological process: canonical NF-kappaB signal transduction; cellular response to tumor necrosis factor; cellular response to virus; non-canonical NF-kappaB signal transduction; positive regulation of canonical NF-kappaB signal transduction; positive regulation of interferon-alpha production; positive regulation of transcription by RNA polymerase II; toll-like receptor 4 signaling pathway; tumor necrosis factor-mediated signaling pathway; anatomical structure morphogenesis; immune response; inflammatory response; innate immune response; response to virus; pattern recognition receptor signaling pathway; response to acetate; response to amino acid; response to cholecystokinin; response to hydroperoxide; response to toxic substance; response to xenobiotic stimulus; skeletal muscle contraction; striated muscle cell differentiation
Cellular component: cytoplasm; cytosol; IkappaB kinase complex; nucleoplasm; nucleus; CD40 receptor complex; cytoplasmic side of plasma membrane
Genetic constraint (gnomAD): Loss-of-function variants: 16 observed, 39.84 expected, observed/expected ratio (o/e) 0.4, 90% interval 0.27 to 0.61. The upper end of that interval is the gene's LOEUF score, 0.61, which puts it in group 2 of 6, group 1 being the genes least tolerant of losing a copy. Missense variants: 320 observed, 439.54 expected, observed/expected ratio (o/e) 0.73, 90% interval 0.66 to 0.8. Synonymous variants: 140 observed, 149.25 expected, observed/expected ratio (o/e) 0.94, 90% interval 0.82 to 1.08.
Gene-disease validity (ClinGen):
ClinGen rates the evidence that CHUK causes each of these diseases.
Bartsocas-Papas syndrome 2 (autosomal recessive): Moderate.
Homologues: Orthologues: macaque CHUK (99% identical), chimpanzee CHUK (99% identical), dog CHUK (98% identical), guinea pig CHUK (96% identical), mouse Chuk (95% identical), rat Chuk (95% identical), rabbit CHUK (94% identical), pig CHUK (77% identical), tropical clawed frog chuk (69% identical), zebrafish chuk (63% identical), Drosophila melanogaster IKKbeta (24% identical). Paralogues in human: IKBKB (51% identical), TBK1 (20% identical), IKBKE (20% identical).
Diseases named in the same sentence as CHUK in open-access papers:
CHUK is named in the same sentence as 212 diseases in open-access papers, as found by Europe PMC text mining. Sharing a sentence is not in itself a finding about the gene and the disease. The quoted sentences say what the papers report.
breast cancer (63 papers, 2010 to 2026). A primary or metastatic malignant neoplasm involving the breast. "This may indicate that CHUK overexpression is an unfavorable predictor of breast cancer treatment with tamoxifen, associated with a shortened time to cancer recurrence." (PMID 39337357, 2024). "Downstream mediators linked to LYN activation of NFκB include MEK, IKKα (or CHUK), PI3K, MAPK and IκB, and there is also support for a role of NFκB activation in BRCA1 loss-of-function-associated breast cancers." (PMID 38149669, 2024). "We used the STRING bioinformatic tool to find biological processes associated with the gene products that we analyzed for their prognostic impact on breast cancer, namely IKKα (CHUK), IKBKB, p50/NFKB1, p65/RELA, NIK (MAP4K4), p52 (NFKB2), RELB, IL-8 (CXCL8), IL6, and MMP-1." (PMID 31602271, 2019). "Consistent with our model, both Notch1 and IKKα (CHUK) mRNA expression are strongly associated with poor survival in TNBC but not ER+ breast cancers." (PMID 30564555, 2018). "In addition, we observed feedback loops concerning nuclear factor kappa B subunit 1 (NFKB1) activation (CHUK, NFKBIA; related to cell survival) in bladder cancer, anti-apoptotic BIRC2/3, and pro-apoptotic TRAF1 factors in breast cancer, respectively." (PMID 28775339, 2017).
prostate carcinoma (52 papers, 2004 to 2025). A carcinoma that arises from epithelial cells of the prostate gland. "The role of CHUK in carcinogenesis may also be confirmed by studies in which CHUK activation was associated with increased promotion of metastasis in prostate cancer." (PMID 39337357, 2024). "Because E2F3 interact with ARNT, we can infer the interactions between two dependent genes AKT3 and CHUK and map to their gene products, protein PKB and IKK in prostate cancer pathway." (PMID 20025723, 2009).
colorectal cancer (17 papers, 2003 to 2025). A primary or metastatic malignant neoplasm that affects the colon or rectum. "For example, in vitro studies on colorectal cancer cell lines showed that the mutated BRAF gene could activate CHUK and then, independently of NF-κB, led to the activation of genes identified as their common targets, which were involved in carcinogenesis promoting." (PMID 39337357, 2024). "Therefore, to further investigate the relationship between KRAS and punctate IKKα expression observed in the present study, future studies in colorectal cancer should investigate the relationship between CHUK mutations, KRAS mutations and IKKα expression in patient samples." (PMID 35173303, 2022). "Therefore, negative regulation of NF-κB through inhibition of CHUK by miR-195-5p or miR-497-5p possibly could sensitize colorectal cancer cells to chemotherapeutic agents." (PMID 31546954, 2019). "Conversely, the expression of the CHUK gene was significantly negatively correlated with tumor purity in READ, indicating higher expression in the tumor microenvironment than in colorectal cancer cells." (PMID 39337357, 2024).
lung carcinoma (16 papers, 2014 to 2025). "Herein, we show two independent in vivo lung cancer models in which CHUK/IKK-α acts as a major NSCLC tumor suppressor." (PMID 31792060, 2019).
colitis (13 papers, 2017 to 2025). Inflammation of the colon. "Moreover, P. candolleana decreased the expression of IKBKB, JUN, CHUK, and TNF-α proteins, thus exerting anti-inflammatory and therapeutic effects on colitis." (PMID 38645561, 2024).
atherosclerosis (10 papers, 2014 to 2023). A disease characterized by the build-up of fatty material and calcium deposition in the arterial wall resulting in partial or complete occlusion of the arterial lumen. "In summary, COVID-19 upregulates both IRAK2 and CHUK, while atherosclerosis only upregulates CHUK, and cardiomyopathy upregulates IRAK2, suggesting that NF-kB activation may be critical in all three conditions." (PMID 34071557, 2021). "ATK2, IKBKB, RAF1, CHUK, TNF, JUN, and PRKCA were mainly involved in fluid shear stress and the atherosclerosis pathways, pathways in cancer, and the PI3K-Akt signaling pathway." (PMID 29177114, 2017). "The targets of ATK2, IKBKB, RAF1, CHUK, TNF, JUN, and PRKCA were mainly involved in fluid shear stress and the atherosclerosis and PI3K-Akt signaling pathways." (PMID 29177114, 2017).
lung adenocarcinoma (10 papers, 2018 to 2025). A carcinoma that arises from the lung and is characterized by the presence of malignant glandular epithelial cells. "Inactivating mutations (2.2% of cases) and hemizygous deletions (22% of cases) of CHUK, the locus encoding IKKα, have been observed in human lung adenocarcinomas." (PMID 30060526, 2018). "In these patients, CHUK deletion was associated with a reduced survival, thus suggesting that IKKα deletion may contribute to the development of a more malignant phenotype of lung adenocarcinomas." (PMID 30060526, 2018).
glioma (9 papers, 2016 to 2023). A benign or malignant brain and spinal cord tumor that arises from glial cells (astrocytes, oligodendrocytes, ependymal cells). "The Kruskal–Wallis test confirmed a significant difference in methylation of all examined genes between glioma types (p < 0.001 for AKT1, AKT3, CHUK, GSK3β, EGFR, PTEN, PIK3AP1; p = 0.032 for AKT2)." (PMID 34209611, 2021). "Lower grade gliomas, the AA group, harbored the highest number of CNA in genes PTEN (50%), PIK3AP1 (49%), and CHUK (49%), while the DA group carried the highest number of CNA in genes AKT1 (15%), AKT2 (11%), and GSK3β (11%)." (PMID 34209611, 2021). "Data on CNA show that genes AKT2, AKT3, CHUK, EGFR, PIK3AP1, and PTEN show an increase in copy number alterations with the increased glioma grade." (PMID 34209611, 2021). "Our investigation on 751 gliomas showed genetic changes of PTEN in 76%, PIK3AP1 and CHUK in 75%, and EGFR in 74% of the total samples." (PMID 34209611, 2021). "Recent studies showed an essential role of CHUK protein product (IKK) in glioma tumorigenesis, while PIK3AP1 acts as a negative regulator of toll-like receptor-induced inflammation." (PMID 34209611, 2021). "Despite the lack of literature data on the behavior of CHUK in gliomas, studies on nasopharyngeal carcinomas show decreased staining of CHUK protein in undifferentiated nasopharyngeal cancers in comparison with differentiated ones." (PMID 34209611, 2021).
melanoma (8 papers, 2014 to 2025). A malignant, usually aggressive tumor composed of atypical, neoplastic melanocytes. "The highest correlations observed with HMOX-1 in patients with melanoma were with FZD2 (rho = 0.54), KEAP1 (rho = 0.59), MAPK13 (rho = 0.68), the “ferroptosis” gene FTL (rho = 0.58), and CHUK (rho = −0.50)." (PMID 35053476, 2022).
osteosarcoma (8 papers, 2009 to 2025). A usually aggressive malignant bone-forming mesenchymal neoplasm, predominantly affecting adolescents and young adults. "This interaction leads to the downstream upregulation of NF-κB through CHUK upregulation, which is known to be highly expressed in osteosarcoma and is implicated in tumorigenesis, and whose inhibition lead to apoptosis and repressed proliferation and invasiveness in cell line models." (PMID 40647416, 2025).
squamous cell carcinoma (8 papers, 2013 to 2024). A carcinoma arising from squamous epithelial cells. "In ESCA, the CHUK gene showed significantly higher expression in the case of adenocarcinoma compared to squamous cell carcinoma (p < 0.001)." (PMID 39337357, 2024).
COVID-19 (5 papers, 2021 to 2025). A disease caused by infection with severe acute respiratory syndrome coronavirus 2. "We found several factors that clearly can be part of driving the inflammatory state in COVID-19 patients, such as CHUK/IKK-α, and IL17A." (PMID 41227320, 2025). "FBA was also able to up-regulate the expression of genes involved in the TLR signaling pathway, such as CHUK, an inhibitor of Nf-kB, TRAF6, a mediator of the inflammatory response and Irf7, which is correlated with COVID-19 gastrointestinal symptoms." (PMID 35164139, 2022).
non-small cell lung carcinoma (5 papers, 2018 to 2024). A group of at least three distinct histological types of lung cancer, including non-small cell squamous cell carcinoma, adenocarcinoma, and large cell carcinoma. "A similar connection was also demonstrated in non-small cell lung cancer cells, which demonstrated elevated CHUK mRNA and protein expression compared to normal cells." (PMID 39337357, 2024).
psoriasis (5 papers, 2016 to 2021). An autoimmune condition characterized by red, well-delineated plaques with silvery scales that are usually on the extensor surfaces and scalp. "Recently, the largest meta-analysis of GWAS for psoriasis has identified 16 novel genetic loci for psoriasis, including CHUK on chromosome 10q24.31, FASLG on chromosome 1q24.3 and IKBKE on chromosome 1q32.1, which are associated with the NF-κB signaling pathway." (PMID 29232931, 2017). "Overexpression of CHUK, IKBKB, NFKBIA, NFKB1, JAK2, STAT1 and STAT3, as inflammation related factors, was detected in the psoriasis model group." (PMID 34834106, 2021).
Bartsocas-Papas syndrome (4 papers, 2016 to 2022). "Moreover, genetic mutations in IRF6 or CHUK have been identified in individuals clinically diagnosed with Bartsocas-Papas syndrome, a form of popliteal pterygium syndrome, supporting the global notion that Irf6 and components of the NFkB pathway are part of the same gene regulatory network." (PMID 27035130, 2016). "Bartsocas-Papas syndrome (BPS, OMIM: 263650), a severe form of PPS, is associated with homozygous pathogenic variants in RIPK4 and CHUK." (PMID 29523099, 2018).
Cerebral ischemia (4 papers, 2013 to 2025). Restriction of arterial blood supply to the brain associated with insufficient oxygenation to support the metabolic requirements of the tissue. "RELA, AKT1, JUN, PRKACA, PTGS2, RAF1 and CHUK were identified as four key targets associated with ischemic encephalopathy." (PMID 38285889, 2024).
prediabetes (4 papers, 2016 to 2023). "Our study found that the level of expression of CHUK mRNA increased progressively from the healthy control to the prediabetic and T2DM groups, indicating its role in the development of prediabetes and T2DM." (PMID 37223012, 2023). "In the current pilot study, the expressions of ZBP1, DDX58, NFKB1 and CHUK were significantly higher in the T2DM group compared to either healthy control or pre-DM patients, which may give us new predictive markers for the development of T2DM in prediabetes patients." (PMID 36139069, 2022).
endometriosis (3 papers, 2018 to 2020). The growth of functional endometrial tissue in anatomic sites outside the uterine body. "High serum IL-6 concentrations in endometriosis patients are probably related to the reduction in conserved helix-loop-helix ubiquitous kinase (CHUK) protein as well as NF-κB inhibitor alpha (NFKBIA) mRNA and the p-NFKBIA/NFKBIA protein ratio." (PMID 32145751, 2020).
mantle cell lymphoma (3 papers, 2021 to 2024). Mantle cell lymphoma is a rare form of malignant non-Hodgkin lymphoma affecting B lymphocytes in the lymph nodes in a region called the ``mantle zone''. "Additionally, this theory is supported by the fact that the upregulation of CHUK leads to the increased proliferation and inhibition of apoptosis in mantle cell lymphoma." (PMID 39337357, 2024). "Overexpression of miR-125b-5p sensitized cutaneous T-cell lymphoma cells to bortezomib via modulation of MAD4 protein, while miR-223-3p is implicated in ibrutinib resistance through regulation of the conserved helix-loop-helix ubiquitous kinase (CHUK)-NFκB signaling pathway in mantle cell lymphoma." (PMID 35628648, 2022).
cocoon syndrome (2 papers, 2024 to 2025). "Human biallelic null variants of CHUK, encoding IKK-α, cause Cocoon syndrome, an embryo-lethal encasement syndrome associated with severe developmental malformations, including abnormally large cranial cysts, abnormal brain structure, and hypoplastic limbs." (PMID 41608125, 2025).
esophageal carcinoma (2 papers, 2019 to 2024). A primary or metastatic malignant neoplasm involving the esophagus. "Our findings reveal that IKBKB and IKBKG are significantly upregulated in all examined cancers, while CHUK is upregulated in esophageal carcinoma and stomach adenocarcinoma." (PMID 39337357, 2024).